SMARCA4 (SWI/SNF related BAF chromatin remodeling complex subunit ATPase 4)
Diseases named in the same sentence as SMARCA4 in open-access papers (continued):
Sharing a sentence is not in itself a finding about the gene and the disease.
cancer (continued). "First, we aimed to assess the potential role of germline PVs in SMARCA4 along with an extended panel of 24 additional (candidate) cancer predisposition genes in a clinical cohort of 206 OC patients (including three SCCOHT index patients) with an AAD ≤40 years." (PMID 37345881, 2023). "Contrary to this paralog synthetic lethality, concomitant loss of SMARCA4/2 occurs in a subset of cancers associated with very poor outcomes." (PMID 37210563, 2023). "Second, we aimed to characterize families with SMARCA4 PVs to gain more insights into SMARCA4‐dependent cancer predisposition and progression." (PMID 37345881, 2023). "Supporting that alanine supplementation competes with glutamine for SLC38A2, the addition of glutamine or ectopic expression of SLC38A2 rescued SMARCA4/2-deficient cancer cells from growth suppression and OXPHOS inhibition caused by alanine treatment." (PMID 37210563, 2023). "Signature 4 is associated with smoking across several cancer types; interestingly, SMARCA4-d is seen in aggressive thoracic sarcomas and strongly enriched among patients with a history of smoking." (PMID 36883553, 2023). "SMARCA4 was originally reported as a tumor suppressor gene due to its inactivating mutations or downregulation of its expression in several cancers and cancer cell lines." (PMID 36902184, 2023). "Taken together, our data support the use of alanine supplementation as an effective therapeutic intervention for SMARCA4/2-deficient cancers." (PMID 37210563, 2023). "ACBI1 demonstrated anti-proliferative effects and induced cell death caused by SMARCA2 depletion in SMARCA4 mutant cancer cells, along with impacts in AML cells reliant on SMARCA4 ATPase activity." (PMID 38044445, 2023). "Our study has revealed multiple druggable vulnerabilities of SMARCA4/2-deficient cancer cells, exploiting their metabolic shift from glucose to glutamine as a key carbon source." (PMID 37210563, 2023). "Mutations overlapping with those in cancer localize to the SMARCA4 ATP binding pocket and nucleosomal DNA-binding residues, the SMARCB1-CTD, and the SMARCA4-BAF core module entry point." (PMID 37500730, 2023). "Mutations in Arp module subunits, ACTB and ACTL6A/B, were nearly selectively enriched in NDDs, whereas mutations in the helicase domain of SMARCA4 were more enriched in cancer." (PMID 37500730, 2023). "Since conventional chemotherapy remains the first-line treatment for SMARCA4/2-deficient cancers, we evaluated the efficacy of alanine supplementation in combination with cisplatin." (PMID 37210563, 2023). "The efficacy of this treatment is being currently tested in other cancers having SMARCB1 or SMARCA4 mutations." (PMID 37093326, 2023). "One of the most frequently mutated subunits of the SWI/SNF complex in human cancers is SMARCA4, which encodes the BRG1 protein." (PMID 37433987, 2023). "Whilst it is well documented that SMARCA4 is frequently mutated in cancers, the functional consequences of specific SMARCA4 mutations on cell physiology are poorly understood and lack useful application in a clinical setting." (PMID 37433987, 2023). "SMARCA4 mutations were found to be present in a diverse set of cancer types at frequencies of up to 16% in solid tumors from 131,668 cancer patients." (PMID 38090508, 2023). "In conclusion, our findings shed light on novel cell types and genes associated with Wnt4Cre-labeled cells and highlight the critical role of Smarca4 in regulating tubular cell differentiation and the expression of the cancer-causing gene Pttg1 in the kidney." (PMID 37727504, 2023). "The spectrum of SMARCA4 mutations in human cancers is large and different mutations appear to lose its ATPase catalytic activities or possess different residual activities." (PMID 37345003, 2023). "In the case of SMARCA4-deficient cancers, the principle of synthetic lethality preferentially targets these cancer cells." (PMID 37433987, 2023).
cancer (continued). "In SMARCA4-deficient cancers that retain SMARCA2 expression, several reports have shown that SMARCA2 acts as a synthetic lethal target, making it a potential therapeutic vulnerability." (PMID 37093326, 2023). "SMARCA4 is involved in many cellular processes, some of which are associated with cancer development, such as differentiation, development, cell adhesion, growth control, metabolism, and DNA repair." (PMID 36902184, 2023). "Loss of SMARCA4 causes downregulation of cyclin D1, and there are data supporting that this vulnerability mediates drug sensitivity to CDK4/6 inhibition in SMARCA4-deficient cancer cells." (PMID 37446319, 2023). "Cancers with concomitant SMARCA4/2 deficiencies are often resistant to chemotherapies and confer a poor prognosis." (PMID 37210563, 2023). "Regarding SNCs with inactivation of one of the SWI/SNF complex genes, SMARCB1-deficient carcinoma was the most frequent subtype followed by SMARCA4-deficient tumors." (PMID 36937407, 2023). "Immunohistochemistry is generally sufficient for diagnosis, although FISH or sequencing can be performed to demonstrate biallelic (homozygous) deletions of the SMARCB1 gene or loss-of-function (mostly truncating) mutations in SMARCA4-deficient carcinomas." (PMID 36941503, 2023). "Among the most frequently mutated subunits of the chromatin remodeling complex throughout SWI/SNF-deficient cancers is the core ATPase subunit BRG1/SMARCA4 and the mutually exclusive ATPase paralog to BRG." (PMID 34982771, 2022). "Many mutations and the functional disruption of the SWI/SNF complex have been reported from cancer genome sequencing in 25% of all cancer types and mutations in SMARCA4 have been reported in BRCA, PRAD, OVCA and PAAD." (PMID 35626007, 2022). "In SMARCA4-deficient cancer, selectively targeting SMARCA2 would be a potential synthetic lethal therapeutic method to treat cancer." (PMID 35978859, 2022). "This permits pharmacological evaluation of the synthetic lethality concept of selectively targeting SMARCA2 in SMARCA4-deficient cancers in vivo and in vitro." (PMID 36216795, 2022). "To test this, we used copy number segment data to calculate mean absolute change in ploidy (as a deviation from 0, which represents normal ploidy) in cancer samples harbouring mutations in the SMARCA4 gene, which encodes BRG1." (PMID 35365638, 2022). "First, germline genetic testing was performed for 112 cancer-predisposing genes using a customized panel that included the SMARCA4 and SMARCB1 genes." (PMID 35200537, 2022). "Dual allosteric inhibitors of the SMARCA2/SMARCA4 ATPases simulate synthetic lethality by curbing proliferation of SMARCA4-deficient cancers." (PMID 35323214, 2022). "The SMARCA4 deficient cancer cells display sensitivity to suppression of the enhancer of zeste homolog 2 (EZH2)." (PMID 35200537, 2022). "Our tool compound, ACBI2, shows selective degradation of SMARCA2 over SMARCA4 in ex vivo human whole blood assays and in vivo efficacy in SMARCA4-deficient cancer models." (PMID 36216795, 2022). "In such a scenario, a descriptive diagnosis of “SMARCA4-deficient sinonasal malignancy consistent with either carcinoma or TCS” can be made prior to resection." (PMID 35307773, 2022). "New tumor entities previously classified as SNUC include SMARCB1-deficient carcinoma, SMARCA4-deficient carcinoma and possibly also IDH2 mutant SNUC." (PMID 36140305, 2022). "Like SMARCA4-deficient carcinomas, they predominantly originate in the nasal cavity (up to 79% of cases) with a striking male predominance (83%) and a wide age range (mean: 50 years; range 10–82)." (PMID 35307773, 2022). "Cancers with SMARCA4 deficiency, a genetic alteration frequently observed in malignant solid tumours or lung adenocarcinomas, for example, show a dependency on the paralogue SMARCA2." (PMID 33941852, 2021). "SMARCA4 gene expression was strongly associated with the gene expression of immunity in various cancers." (PMID 34675941, 2021).
cancer (continued). "The DNA binding subunit ARID1A, and the catalytic subunit SMARCA4 (BRG1) are the two most mutated BAF subunits across cancer types." (PMID 33826602, 2021). "Here, we discover that SMARCA4/2 loss inhibits chemotherapy-induced apoptosis through disrupting intracellular organelle calcium ion (Ca2+) release in these cancers." (PMID 34518526, 2021). "A statistically positive correlation of SMARCA4 expression and the estimated infiltration value of cancer-associated fibroblasts is observed for the TCGA tumors of CESC and HNSC-HPV− but noted a negative correlation for TGCT and THYM." (PMID 34675941, 2021). "Together, these data indicate that quisinostat treatment can indirectly restore IP3R3 expression and rescue Ca2+ flux in SMARCA4/2-deficient cancer cells." (PMID 34518526, 2021). "SMARCA4 (BRG1) is another SWI/SNF subunit whose encoding gene is recurrently mutated in cancer and for which there is now an immunohistochemical biomarker." (PMID 33921435, 2021). "Since the median age at cancer diagnosis in SMARCA4 mutation carriers is lower as compared to BRCA1/BRCA2 mutation carriers, the prophylactic surgery should be offered at least earlier, preferably below the age of 22." (PMID 33907931, 2021). "Together, these findings imply that the lack of SMARCA4 confers vulnerability to KDM6s inhibition on cancer cells, and that the intrinsically low levels of KDM6s, caused by the defective function of SMARCA4, underpin these effects." (PMID 34262032, 2021). "Cancer-associated mutations in the ATP-binding cleft of human SMARCA4 caused a comparable ~ 2-fold reduction in FRAP recovery kinetics in diploid cells." (PMID 34313222, 2021). "Our own previous work produced the first evidence that SMARCA4 is genetically inactivated in cancer and that SMARCA4 deficiency prevents the response to pro-differentiation stimuli in cancer cells." (PMID 34262032, 2021). "Next, we explored the possibility of using HDACi to restore chemotherapy sensitivity in SMARCA4/2-deficient cancer cells." (PMID 34518526, 2021). "SMARCA4-deficient cancers are a new cancer type in the upcoming WHO classification of thoracic tumors." (PMID 33674910, 2021). "To corroborate our results, we sought to perform the reverse experiments by restoring SMARCA4 or SMARCA2 in SMARCA4/2-deficient cancer cells." (PMID 34518526, 2021). "Taken together, our data provide a proof-of-concept treatment strategy for enhancing chemotherapy response in patients affected by SMARCA4/2-deficient cancers." (PMID 34518526, 2021). "Our study provides insights into the molecular mechanisms of SWI/SNF loss in promoting drug resistance and suggests a potential therapeutic strategy to enhance chemotherapy response in patients affected by SMARCA4/2-deficient cancers." (PMID 34518526, 2021). "Here, the authors show that SMARCA4/2 deficiency in cancer cells reduces the expression of the ER-Ca2+ channel IP3R3 and subsequently calcium transfer to the mitochondria, which inhibits apoptotic cell death." (PMID 34518526, 2021). "The potential association between SMARCA4 alteration and the clinical survival prognosis of cases with different types of cancer was analyzed." (PMID 34675941, 2021). "Reactivation of SMARCA2 by a histone deacetylase inhibitor rescues IP3R3 expression and enhances cisplatin response in SMARCA4/2-deficient cancer cells both in vitro and in vivo." (PMID 34518526, 2021). "Since SMARCA4 is also frequently inactivated in NSCLC, we investigated the association of SMARCA4 expression with chemotherapy response in this cancer type." (PMID 34518526, 2021). "Although the ARID1 subunit of BAF and the PBRM1 subunit of PBAF exhibit the highest mutation prevalence, SMARCA4-mutant cancers are typically more aggressive and are associated with a poorer prognosis." (PMID 33941852, 2021).
cancer (continued). "For example, SMARCA4 expression level in HNSC-HPV− is correlated with the infiltration level of cancer-associated fibroblasts (cor = 0.2, p = 5.46e−05) based on the MCPCOUNTER algorithm." (PMID 34675941, 2021). "We found that naturally occurred SMARCA4/2-deficient cancer cells are more resistant to chemotherapy, which is in line with previous reports showing that SCCOHT is typically more resistant to conventional chemotherapy in both cell models and patients." (PMID 34518526, 2021). "The epigenetic regulator SMARCA4 is a member of the SWI/SNF chromatin remodeling family that has been implicated in loss-of-function (LoF) mutations or downregulation in various cancers." (PMID 34771636, 2021). "The PROTAC ACBI1 has now led to a renaissance of bromodomains as drug targets in SMARCA4-deficient cancers." (PMID 33941852, 2021). "Our results reveal a mechanism linking SMARCA4/2 loss to chemoresistance by inhibiting apoptosis induction and suggest a potential therapeutic strategy for improving treatment for SMARCA4/2-deficient cancers." (PMID 34518526, 2021). "To date, the majority of SMARCA4-DTTs have been reported as SMARCA4-deficient thoracic sarcomas; however, there are increasing reports of carcinomas." (PMID 34181162, 2021). "The purpose of the case report is to provide practical information and useful recommendations on the diagnosis, management, and treatment of SMARCA4-deficient carcinoma of the uterine cervix resembling SCCOHT." (PMID 34970085, 2021). "It has been observed that cancer cell lines are deficient in SMARCA4 and that ectopic expression of SMARCA4 can rescue cell-cycle inhibition." (PMID 32629987, 2020). "Paradoxically, SMARCA4 is also reported to be mutated and over‐expressed in a variety of malignant tumours, including melanoma, gastric and prostate cancers." (PMID 32162380, 2020). "Here, the authors detect more than 10,000 SMARCA4 variants across different cancer subtypes and find hotspot mutations throughout the helicase domain, which reduce remodeling activity." (PMID 33144586, 2020). "Albeit associated with cell-cycle promoting E2F3a, a known prognosticator in OC31, high SMARCA4 expressing cancers were associated with improved survival." (PMID 33230143, 2020). "Although cancer-associated mutations are present throughout SMARCA4, mutations to the two ATPase lobes are commonly found in cancer." (PMID 32629987, 2020). "SMARCA4 and SMARCA2 function as mutually exclusive catalytic subunits of the SWI/SNF complex, and Hoffman et al112 demonstrated that depletion of SMARCA2 in SMARCA4‐deficient cancer cells led to cell cycle arrest and senescence." (PMID 32162380, 2020). "This lethal cancer, which affects young women, is characterized by an aggressive clinical course, poor prognosis, and a recently discovered pathognomonic mutation in SMARCA4." (PMID 32677969, 2020). "In silico analysis of cancer-associated mutations of SMARCA4 suggest that they destabilize the HSA α-helix." (PMID 32629987, 2020). "Genetic studies have revealed high frequencies of SMARCA4 mutations in ovarian, thoracic, lung, and prostate cancer." (PMID 32629987, 2020). "SMARCA4/BRG1 and SMARCA2/BRM, the two mutually exclusive catalytic subunits of the BAF complex, display a well-established synthetic lethal relationship in SMARCA4-deficient cancers." (PMID 31406271, 2019). "In the case of SCCOHT, the critically low level of cyclin D1 caused by SMARCA4 loss is a cancer vulnerability that can also be targeted by the same inhibitors." (PMID 30718506, 2019). "By applying SMARCA2 reconstitution and knock-out strategies in ESCC cell models, we define a novel synthetic lethal relationship reciprocal to the SMARCA2 dependency observed in SMARCA4-deficient cancer cells." (PMID 31406271, 2019). "Re-expression of SMARCA4 or SMARCA2 into cancer cell lines deficient for these proteins decreases cell proliferation." (PMID 29391527, 2018).
cancer (continued). "SMARCA4 loss has been reported in dedifferentiated carcinomas and has been associated with rapid progression." (PMID 29976164, 2018). "According to previous researches, SMARCA4 is one of the most broadly mutated subunits, developing an understanding of the mechanisms by which mutation of SMARCA4 drives cancer and of the vulnerabilities created carries major disease relevance." (PMID 28055962, 2017). "SMARCA4 is mutated or deleted in more cancer types than NSCLC36, 37, 43, and a relationship between SNF5 mutations and AURKA was reported for rhabdoid tumours." (PMID 28102363, 2017). "Mutations or changes in the expression of SMARCA4 or other BAF complex subunits are associated with a wide variety of cancers, including lymphoid malignancies." (PMID 26842758, 2016). "Although mutations in SMARCA4 have been described in more common cancers such as lung adenocarcinomas, they occur in a fraction of cases and are not the obvious drivers of oncogenesis." (PMID 25676695, 2015). "Exciting new evidence is emerging from the discovery that ARID1A-mutant cancer cells are highly vulnerable to loss of ARID1B expression, and similarly for BRG1/SMARCA4-mutated cancers to the loss of BRM/SMARCA2." (PMID 25927994, 2014). "ATRX, ARID1A, PBRM1, and SMARCA4 are also among the most frequently mutated chromatin factors in cancer, and are all components of the chromatin remodeling complex SWI/SNF, which has been shown to facilitate double-strand break repair." (PMID 25484917, 2014). "The researchers depleted SMARCA2 in SMARCA4-deficient cancer cell lines and xenograft models and observed cycle arrest, induction of senescence, and increased level of the repressive marker H3K9me3." (PMID 25391308, 2014). "To date, only two H&N SMARCA4-deficient carcinomas have been reported outside the sinonasal region." (PMID 41803273, 2026). "Large genomic studies have identified SMARCA4 mutations in approximately 4% of all cancers, with NSCLC, cancer of unknown primary, and endometrial, breast, and colon cancer having the highest prevalence." (PMID 41387924, 2025). "Moreover, KRAS/SMARCA4 co-mutated patients across multiple NSCLC studies were found to have inferior survival outcomes throughout various types of cancer treatment analysis, including chemotherapy, ICI, and targeted therapy." (PMID 41007704, 2025). "SMARCA4 is a BRG1 protein-encoding gene identified as an oncogene in many cancers." (PMID 40223925, 2025). "In this study, we show that simultaneous inhibition of a paralog pair (CBP and p300) causes synthetic lethality in SMARCA4/SMARCA2-deficient cancer cells and SS18–SSX fusion cancer cells; these results are similar to those obtained for SMARCB1-deficient cancer cells." (PMID 39625239, 2025). "SMARCA4-deficient cancer cells are associated with increased replication stress, one of the major causes of genomic instability, which may lead to cancer." (PMID 41641123, 2025). "Interestingly, the same study found that the OXPHOS inhibitor suppressed cancer cell proliferation when SMARCA4 loss triggered a shift from glycolysis to OXPHOS." (PMID 41392981, 2025). "Because SMARCA4/SMARCA2-deficient and SS18–SSX fusion cancer cells depend on transcriptional upregulation of KREMEN2 due to SMARCA4/SMARCA2 deficiency and SS18–SSX fusion, we clarified that synthetic lethality is induced by repressing expression of KREMEN2 by simultaneous inhibition of CBP/p300." (PMID 39625239, 2025). "SMARCA4-UT is a rare malignant tumor associated with a poor prognosis." (PMID 41142791, 2025).